ALDH2 (aldehyde dehydrogenase 2 family member)
Description:
Required for clearance of cellular formaldehyde, a cytotoxic and carcinogenic metabolite that induces DNA damage.
Synonyms: ALDM; ALDH-E2; ALDHI
Tractability: Small molecule: an approved drug acts on it; a structure with a bound ligand is known; a high-quality ligand is known; it has a high-quality binding pocket; it belongs to a druggable protein family. PROTAC: UniProt records ubiquitination sites on it; ubiquitination databases record sites on it; its protein half-life has been measured; a small molecule that binds it is known.
Target class: Enzyme; Oxidoreductase
Safety:
Unwanted effects reported when the protein is acted on. In parentheses: how it was acted on, where the effect was seen, and who reports it.
alcoholism (source: ClinPGx)
Gene: Protein-coding gene on chromosome 12 (111,766,887 to 111,817,532, forward strand). Ensembl gene ENSG00000111275.
Subcellular location: Mitochondrion matrix
Pathways (Reactome):
Metabolism: Ethanol oxidation
Metabolism of proteins: Mitochondrial protein degradation
Muscle contraction: Smooth Muscle Contraction
Neuronal System: Metabolism of serotonin
Gene Ontology:
Molecular function: acetaldehyde dehydrogenase (NAD+) activity; aldehyde dehydrogenase (NAD+) activity; carboxylesterase activity; oxidoreductase activity, acting on other nitrogenous compounds as donors, with NAD or NADP as acceptor; NAD binding; phenylacetaldehyde dehydrogenase (NAD+) activity; aminobutyraldehyde dehydrogenase (NAD+) activity; formaldehyde dehydrogenase (NAD+) activity; oxidoreductase activity; retinal dehydrogenase (NAD+) activity; succinate-semialdehyde dehydrogenase (NAD+) activity
Biological process: aldehyde catabolic process; cellular detoxification of aldehyde; dopamine catabolic process; ethanol catabolic process; nitroglycerin metabolic process; ethanol metabolic process
Cellular component: extracellular exosome; mitochondrion; mitochondrial matrix
Genetic constraint (gnomAD): Loss-of-function variants: 40 observed, 52.65 expected, observed/expected ratio (o/e) 0.76, 90% interval 0.59 to 0.99. The upper end of that interval is the gene's LOEUF score, 0.99, which puts it in group 4 of 6, group 1 being the genes least tolerant of losing a copy. Missense variants: 570 observed, 689.32 expected, observed/expected ratio (o/e) 0.83, 90% interval 0.77 to 0.89. Synonymous variants: 291 observed, 279.56 expected, observed/expected ratio (o/e) 1.04, 90% interval 0.94 to 1.15.
Cancer hallmarks: genome instability and mutations (suppresses)
Homologues: Orthologues: chimpanzee ALDH2 (99% identical), rat Aldh2 (95% identical), guinea pig ALDH2 (95% identical), mouse Aldh2 (95% identical), dog ALDH2 (93% identical), rabbit ALDH2 (93% identical), pig ALDH2 (85% identical), tropical clawed frog aldh2 (80% identical), zebrafish aldh2.1 (76% identical), zebrafish aldh2.2 (75% identical), Drosophila melanogaster Aldh (70% identical), Caenorhabditis elegans alh-1 (67% identical), and 1 more. Paralogues in human: ALDH1B1 (74% identical), ALDH1A1 (66% identical), ALDH1A2 (66% identical), ALDH1A3 (64% identical), ALDH1L2 (48% identical), ALDH1L1 (48% identical), ALDH9A1 (40% identical), ALDH8A1 (35% identical), ALDH5A1 (33% identical), ALDH6A1 (29% identical), ALDH7A1 (29% identical), ALDH4A1 (27% identical), and 5 more.
Diseases named in the same sentence as ALDH2 in open-access papers:
ALDH2 is named in the same sentence as 316 diseases in open-access papers, as found by Europe PMC text mining. Sharing a sentence is not in itself a finding about the gene and the disease. The quoted sentences say what the papers report.
alcoholism (96 papers, 1995 to 2025). "Comparable findings have been reported for ALDH2, specifically the rs671 variant, which shows robust associations with alcohol dependence and alcohol-related traits, including maximum drinks and flushing response, particularly in East Asian populations." (PMID 41465120, 2025). "It has been reported that ALDH2 dysfunction is associated with a variety of human diseases, including cardiovascular diseases, diabetes mellitus, neurodegenerative diseases, alcohol-induced pathophysiology, and upper aerodigestive track cancers." (PMID 39416436, 2024). "An ALDH2 coding variant protects against alcoholism by producing an inactive ALDH enzyme, leading to the accumulation of acetaldehyde." (PMID 39456347, 2024). "On the contrary, the ALDH2 rs671 GA/AA genotypes significantly reduced the risk of alcohol‐induced mental disorders by 87%, alcohol dependence syndrome by 83%, and alcohol abuse by 66%." (PMID 35670037, 2023). "Specific alleles of rs1229984 and rs671 in the ADH1B and ALDH2 genes, accordingly, lead to physical reactions like facial flushing and nausea after alcohol consumption, lowering the risk of alcohol dependence." (PMID 37628681, 2023). "These suggested that selective loss of Aldh2 in neurons was somehow protective against the degree of alcoholism in mice, similar to the case found in humans." (PMID 36691110, 2023). "Studies have shown that the ALDH2 polymorphism, ALDH2*2, is protective against alcoholism because it acts in a suppressive manner against excessive alcohol intake due to the discomfort caused by drinking." (PMID 37693648, 2023). "Since acetaldehyde accumulation induces an unpleasant effect on the body, people carrying the ALDH2 rs671 A allele are less likely to drink and therefore have a lower risk of alcohol dependence." (PMID 35670037, 2023). "Studies have found that patients with an inactivating point gene polymorphism coding for ALDH2_rs671 (AG/AA) are markedly protected against alcoholism." (PMID 36200595, 2023). "Clinical trials have been conducted using drug compounds targeting one of the three causal genes, including ALDH2 (ranked as high confidence level in our findings), for alcohol dependency and parasite infection (two drugs, phase 4)." (PMID 35733147, 2022). "In the present prospective study of Chinese population, we observed broadly similar effect modifications of ALDH2‐rs671 genotypes on risks for IARC alcohol‐related and oesophageal cancers associated with alcohol consumption, as in previous studies." (PMID 35048370, 2022). "We prospectively assessed 746 patients with cirrhosis with HBV infection and/or heavy alcoholism for ALDH2 rs671 polymorphism analysis." (PMID 35877121, 2022). "Regardless of ADH1B genetic polymorphisms, the results also indicate that ALDH2*2 plays a major role for acetaldehyde-related physiological negative responses and prove the genetic protection against the development of alcoholism in East Asians." (PMID 34439848, 2021). "The present study showed that the never or former flushing by the simple flushing questionnaire was a strong independent risk factor of alcohol dependence in any ALDH2 and ADH1B genotype combination carriers in both men and women." (PMID 34310648, 2021). "In male Han Chinese, the ADH1B p.H48R variation was positively associated with alcohol dependency; however, the ALDH2 p.E504K variation was negatively associated with alcohol dependency." (PMID 34073884, 2021). "ALDH2 is also the most replicated risk gene for excessive alcohol use and alcohol-related complications." (PMID 34366936, 2021). "Functional variant alleles of ADH1B*2 and ALDH2*2 have been consistently replicated to show protection against developing alcoholism and confined in the Asian population, including Han Chinese, Japanese, and Koreans." (PMID 34439848, 2021).
alcoholism (continued). "The homozygosity of variant ALDH2*2 gene allele nearly fully protected against alcoholism; however, ALDH2*1/*2 heterozygosity only had partial protection for developing alcoholism." (PMID 34439848, 2021). "Previous GWAS results revealed that both ADH1B and ALDH2 variants are associated with alcohol dependency in Chinese people; however, only the ALDH2 variant is associated with drinking behavior in Japanese people." (PMID 34073884, 2021). "Recall bias of the responses to the questionnaire cannot be ruled out, and the results regarding associations of alcohol flushing with ALDH2 genotype and susceptibility to alcohol dependence differ according to how the question about alcohol flushing is posed." (PMID 34310648, 2021). "Genome-wide association study (GWAS) results revealed that both ADH1B p.H48R and ALDH2 p.E504K variants are associated with alcohol dependency in Chinese people; however, only the ALDH2 p.E504K variant is associated with drinking behavior in Japanese people." (PMID 34073884, 2021). "The 12q24 locus on IONFH and alcohol-associated ONFH contains ALDH2 (alcohol dehydrogenase 2), encoding a major enzyme in alcohol metabolism." (PMID 29118346, 2017). "The del− genotype was associated with alcoholism, especially in male population, and alcoholic patients with the del− continued to drink despite they had protective ALDH2*2 and ADH1B*2 alleles." (PMID 29234453, 2017). "We find that disulfiram (Antabuse), an ALDH2 inhibitor in widespread clinical use for the treatment of alcoholism, selectively eliminates BRCA1/2‐deficient cells." (PMID 28729482, 2017). "We investigated the association between single nucleotide polymorphisms (SNPs) in ALDH2, which has been associated with alcohol dependence and several types of diseases, and the risk of drug addiction in a Chinese Han population." (PMID 28052001, 2017). "The missense variant rs671 in ALDH2 significantly affects the risk of developing alcohol dependence and its sequelae in East Asian populations but this variant is largely absent in European populations." (PMID 28594837, 2017). "In particular, the ADH1B*2, ADH1B*3, ADH1C*1, and ALDH2*2 alleles have shown protective associations with alcohol dependence." (PMID 27163368, 2016). "Certain genetic variants (i.e., alleles)—particularly the ADH1B*2, ADH1B*3, ADH1C*1, and ALDH2*2 alleles—have been associated with lower rates of alcohol dependence." (PMID 27163368, 2016). "The ALDH2 genotype demonstrates a strong association with alcohol dependence among individuals with a comorbid anxiety disorder." (PMID 26111525, 2015). "Based on two studies that included people with alcohol dependence (median 120 g/day of pure alcohol intake), people with the inactive variant of ALDH2 had an RR of 13.00 (95% CI: 8.99–18.80) compared to those with the active variant." (PMID 26229204, 2015). "We previously demonstrated that ADH1B*47Arg and ALDH2*487Lys were dramatically associated with the risk of alcoholism in a Korean population." (PMID 24690209, 2014). "Genetic studies suggested that ALDH2 was associated with alcohol dependence, bipolar I disorder, and cardiovascular diseases." (PMID 24454952, 2014). "These adverse reactions in subjects with ALDH2*487Lys, as a result of excessive acetaldehyde accumulation, tend to reduce alcohol consumption, consequently reducing the risk of alcoholism." (PMID 24690209, 2014). "There is evidence that the ALDH2*2 gene encoding the inactive variant of ALDH2 protects nearly all carriers of this gene from alcoholism." (PMID 21318009, 2010). "Deficiency in ALDH2 due to point mutation in the active ALDH2*1 gene, significantly alters blood acetaldehyde levels and vulnerability for alcoholism." (PMID 20617031, 2010). "In fact, the protective effect of ALDH2*2 is the most widely reproduced association of a specific gene with alcoholism." (PMID 17718394, 2007).
alcoholism (continued). "The severe effects of the ALDH2*2 variant on acetaldehyde levels and alcoholism risk demonstrate that the mitochondrial ALDH2 enzyme normally is the most important enzyme for eliminating acetaldehyde from the body and keeping acetaldehyde levels extremely low." (PMID 17718394, 2007). "The region on chromosome 12, detected in alcoholics with low P300 amplitude, lies in the vicinity of the mitochondrial aldehyde dehydrogenase gene (ALDH2), long implicated to have a role in alcohol dependence." (PMID 16451617, 2005). "People who are heterozygous experience a flushing response after consuming alcohol and have a substantially reduced risk of alcohol dependence compared with people who are homozygous for the functional ALDH2–1 allele." (PMID 12875047, 2002). "People who are homozygous for the defective ALDH2–2 allele experience an even more severe response to alcohol and have a risk of alcohol dependence that is close to zero." (PMID 12875047, 2002). "Analyses of the relationships between alcohol-related genes, such as ALDH2, and behavior can provide insight into the determinants of alcohol-use patterns of people at various levels of genetic risk for alcoholism." (PMID 31798054, 1995). "Similarly, genetic factors also influence the metabolism of alcohol, with enzymes encoded by ADH1B and ALDH2 impacting alcohol dependence." (PMID 41465120, 2025). "Generally, individuals with the ADH1B*2 variant or the low-activity ALDH2 variant tend to consume less alcohol because of the toxic and unpleasant effects of acetaldehyde, which offers protection against alcohol dependence and alcohol-related hepatocellular carcinoma." (PMID 40943250, 2025). "ALDH2 is a well-known gene associated with an increased risk of alcoholism." (PMID 39456347, 2024). "Therefore, a combination of a high metabolism activity (ADH1B*2 and ADH1B*3) and the inactive form ALDH2*2 will be associated with less alcohol dependence due to the “flushing” effect, an unpleasant phenomenon after alcohol consumption." (PMID 38886650, 2024). "Recent studies showing that neurofilament light chains, a marker of neuroaxonal injury, are more increased in alcohol dependence patients with the ALDH2 deficient polymorphism provide more support for this hypothesis." (PMID 37693648, 2023). "Previous research has focused on identifying which genes may be more strongly associated with alcoholism, with Edenberg summarizing that ALDH2*2 may be protective against alcohol dependence." (PMID 35456053, 2022). "If positive central effects are more pronounced, individuals with inactive ALDH2 may lack protection from alcoholism and may be susceptible to excessive alcohol consumption." (PMID 35869160, 2022). "This could be partly attributable to the existence of additional causes of alcohol flushing besides the ALDH2 genotype in persons susceptible to alcohol dependence." (PMID 34310648, 2021). "The combination of the alcohol flushing status and ALDH2 plus ADH1B genotype may have a better performance for predicting the alcohol-dependence risk in comparison with alcohol flushing alone or genotyping alone." (PMID 34310648, 2021). "Combined evaluation of the alcohol flushing status and the ALDH2 plus ADH1B genotype may show superior ability than that of either alone for predicting the risk of alcohol dependence." (PMID 34310648, 2021). "Our previous multiple logistic regression analyses also suggest that ADH1B*2 and ALDH2*2 may independently influence the risk for alcoholism." (PMID 34439848, 2021).
alcoholism (continued). "The risk of alcohol dependence (AD) in Japanese men and women was evaluated according to combinations of alcohol flushing and aldehyde dehydrogenase-2 (ALDH2, rs671) and alcohol dehydrogenase-1B (ADH1B, rs1229984) genotypes, all of which are known to determine AD susceptibility in Asians." (PMID 34310648, 2021). "ALDH: Similar to ADH and CYP2E1 variants, polymorphisms in the ALDH2 demonstrate a vital role in regulating ALDH2 activity and are hypothesized to alter genetic susceptibility to alcohol dependence and alcohol-induced liver diseases." (PMID 32143280, 2020). "It has been reported that both ADH1B and ALDH2 present strong association with alcohol dependence." (PMID 32300124, 2020). "To investigate the association between ALDH2 and drug addiction risk, we genotyped eight variants in ALDH2 associated with alcohol dependence and performed a comprehensive association analysis to identify SNPs associated with drug addiction risk in a Chinese Han population." (PMID 28052001, 2017). "Thus, results from a meta-analysis study found that both the diagnostic system used in a study and the recruitment strategy used to identify study participants moderated the effects of ALDH2*2 on risk of alcohol dependence." (PMID 27163368, 2016). "Thus, Asians who carry the ALDH2*2 allele show a greater protective effect (i.e., a lower risk of alcohol dependence) from the ADH1B*2 allele than do people who only carry the functional ALDH2*1 allele." (PMID 27163368, 2016). "A meta- analysis of studies of Asian samples indicated that having one ALDH2*2 allele was associated with a four- to fivefold reduction in alcohol dependence (OR = 0.22), and having two ALDH2*2 alleles was associated with an eight- to ninefold reduction in alcohol dependence (OR = 0.12)." (PMID 27163368, 2016). "With regard to ALDH, the ALDH2*2 allele has shown the largest association with alcohol dependence." (PMID 27163368, 2016). "Since substance dependence requires interaction of multiple genes, the combination of genotypes ADH2*2, CYP2E1*1 combined with genotype homozygous ALDH2*1 found in this study could be leading to the population to a potential risk to alcoholism." (PMID 26848198, 2015). "Because of these acute effects after alcohol ingestion, Glu504Lys SNP of ALDH2 gene is protective against the development of alcoholism and perhaps may decrease the risk of chronic diseases caused by alcohol overconsumption." (PMID 26491656, 2015). "In addition, the AF indicates that alcoholism in 39.5% of TB patients in the Korean population can be attributed to the detrimental effect of ALDH2*487Glu, which suggests that this polymorphism is one of the genetic components of TB, at least among Koreans." (PMID 24690209, 2014). "Consequently, the ALDH2*2 allele is the strongest genetic modifier of drinking behavior and reduces the risk of alcohol-related diseases, such as alcoholism, alcohol-related liver cirrhosis, chronic pancreatitis, DM and hypertension." (PMID 24028448, 2013). "Likewise, an ALDH2 variant with reduced activity results in acetaldehyde buildup and also has a protective effect against alcoholism." (PMID 23134050, 2012). "Indeed, genetic epidemiologic studies have indicated that the ALDH2*2 allele inhibits the development of alcoholism." (PMID 21672255, 2011). "Prevalence of the ALDH2*1 allele is associated with alcoholism." (PMID 20617031, 2010). "For example, one variant in the ALDH2 promoter region that occurs in all major ethnic groups affects gene expression and may influence the risk for alcoholism." (PMID 17718394, 2007). "The presence of even a single ALDH2*2 allele is strongly protective against alcohol dependence." (PMID 17718394, 2007). "ADH1B and ALDH2 are the genes most strongly associated with risk for alcoholism." (PMID 17718394, 2007).